TNF (tumor necrosis factor)
Diseases named in the same sentence as TNF in open-access papers (continued):
Sharing a sentence is not in itself a finding about the gene and the disease.
inflammation (continued). "Indeed, the observation that flagellin does not promote wound healing, unlike alternative microbial products tested, may be a functional consequence of increased TLR5-driven TNF-α, with increased SOCS3, observed in chronic intestinal inflammation, exacerbating pathological TNF-α secretion." (PMID 25377316, 2015). "Since the enzyme plays an important role in converting TNF-α to its soluble form, counteracting the increase in TNF-α concentration in inflammatory disorders by targeting TACE enzyme could provide a potential therapeutic strategy to check inflammation diseases." (PMID 25336399, 2014). "At week 12, the GMA-SS exposure induced pulmonary inflammation in both strains, without consistent changes in markers of systemic inflammation (CRP, MCP-1, IL-6 and TNFα)." (PMID 31924220, 2020). "While we have not analyzed the molecular mechanism leading to heart inflammation during MS, experimental data has shown that Toll-like receptor 4 (TLR4) stimulation by fatty acids promotes TNF-α, IL-6, and IL-1β gene expression." (PMID 29201273, 2017). "Our results reveal that in the context of lung inflammation, ADAM17 participates in the shedding of IL-6R, but in contrast to TNF-α and L-selectin, ADAM17 is not the primary sheddase of leukocyte IL-6R." (PMID 21603616, 2011). "The subacute phase of OVA-induced lung inflammation evaluated 4 weeks after the last challenge is characterized by the decrease in the number of leukocytes and granulocytes as well as IL-6 in the BAL fluid, but not to healthy levels, while TNF-α reached the values of healthy animals." (PMID 35625754, 2022). "Similarly, MAPK inhibitors SP600125 and SB203580, but not PD98059, significantly reduced TNF-α and IL-1β in BALF of UCP2-Ad + LPS mice compared to UCP2-NC + LPS mice, demonstrating that enhanced UCP2 expression increased LPS-induced lung inflammation via the JNK and p38 MAPK pathways." (PMID 27057102, 2016).
bacterial infection (724 papers, 2001 to 2026). "Using ELISA assays, we measured the corneal levels of TNF-α and IL-8, which are pro-inflammatory cytokines associated with corneal tissue damage resulting from bacterial infections." (PMID 41384791, 2025). "After obtaining nearly all of the results, we found that the variable “any bacterial infection” was statistically associated with IL-1β (p-value < 0.05), IL-6 (p-value < 0.05), IL-8 (p-value < 0.05), IL-10 (p-value < 0.05), and TNF-a (p-value < 0.05)." (PMID 40732663, 2025). "IL-6 and TNF-α played critical roles in bacterial infections, while RSV infection was directly associated with IL-8, an important chemokine involved in neutrophil recruitment." (PMID 40770421, 2025). "The use of immunosuppressive therapy, specifically adalimumab, a tumor necrosis factor alpha (TNF-α) inhibitor, is associated with increased incidence, morbidity, and mortality in the context of bacterial infections." (PMID 41531628, 2025). "To investigate this discrepancy, we quantified IL-6 and TNF-α as main cytokines against bacterial infection by enzyme-linked immunosorbent assay (ELISA)." (PMID 40823821, 2025). "Taken together, TNF and Mapk11, which encode TNF-α and p38β respectively, are shared between both parasitic and bacterial infection pathways." (PMID 40206211, 2025). "A recent publication suggested that Ifi207-depleted cells had a diminished TNFα and IFNβ response to bacterial infection because of the loss of RNAPolII at the promoters of the genes." (PMID 38860764, 2024). "Proinflammation-associated factors of TNF-α and IL-6 in the tissue were studied to further confirm the inflammation regulation prompted by bacterial infection." (PMID 38167880, 2024). "Our study uses flagellin-deficient L. pneumophila to highlight that TNF also licenses rapid activation of multiple inflammasomes to restrict bacterial infection independently of flagellin and NAIP5/NLRC4 inflammasome activation." (PMID 37279255, 2023). "Pro-inflammatory cytokines associated with viral or bacterial infections such as tumor necrosis factor-alpha (TNFα), interleukin-6 (IL6), or interleukin-1beta (IL1β) are known to affect many liver functions or synthetic activities." (PMID 36499207, 2022). "Evidence has been accumulated that severe bacterial infections and septic shock are associated with increased levels of plasma cytokines such as tumor necrosis factor-α (TNF-α) and interleukins (IL)-1." (PMID 36038815, 2022). "We found that IL-17/TNF-α, a stimulus that is associated with bacterial infection and neutrophilic infiltration, is particularly effective in enhancing ATP12A expression and function." (PMID 36219481, 2022). "Forty-three biomarkers were investigated, of which 6 (CRP, PCT, IL-8, IL-6, IL-10, and TNFα) were significantly associated with bacterial infection at admission, studied in multiple studies, and provided predictive data." (PMID 35372147, 2022). "PCT is a diagnostic marker of bacterial infection, which is produced by LPS, TNF-α and IL-6 acting on neuroendocrine cells or special cells in the liver and spleen." (PMID 35436978, 2022). "Consistently, LXR-knockout (KO) mice were found to be susceptible to bacterial infection owing to the impaired phagocytic activity of Kupffer cells and enhanced TNF-α production of the recruited macrophages." (PMID 35008905, 2022). "The inflammatory factors TNF-α, IL-6, and IL-1β, are closely associated with the response to bacterial infection." (PMID 34858427, 2021). "Further, treatment by øKp_Pokalde_002 significantly reduced the inflammations caused by bacterial infection and downregulated the levels of the pro-inflammatory cytokine (TNF-α and IL-6) expression." (PMID 34485172, 2021). "TNF expression level is positively correlated with the mortality caused by some bacterial infections." (PMID 34869718, 2021).
bacterial infection (continued). "Several bacterial infections and host genetic backgrounds, including TNFα SNP polymorphisms, play important roles in recurrent spontaneous abortions (RSA)." (PMID 35392343, 2021). "During bacterial infections, LPS can invade tissues and interact with immune cells, causing the release of several pro-inflammatory mediators such as TNF-α and IL-1." (PMID 33765924, 2021). "Meanwhile, tocilizumab exhibited similar risk of opportunistic and bacterial infection but lower TB reactivation in comparison to anti-TNF therapy." (PMID 33930048, 2021). "Specifically, CT and TT genotypes of rs3804099 are linked with resistance to bacterial infection due to higher TNF-a, IL-1B and IL-6 production in peripheral blood monocytes than CC homozygotes." (PMID 33328979, 2020). "Loss of this ability led to the increased susceptibility of the cells to TNF- or TRAIL-induced cell death during bacterial infection." (PMID 32432056, 2020). "It was found that TNF-α increases the susceptibility of zebrafish to viral (spring viremia of carp virus) and bacterial infections (Streptococcus iniae)." (PMID 31572451, 2019). "LZD (20 mg/kg, 40 mg/kg, or 80 mg/kg q12h) pretreatment led to decreased IFN-γ and TNF-α production, decreased weight loss, and lower bacterial burdens at 24 h post bacterial infection in comparison with vehicle-treated controls." (PMID 31849655, 2019). "TNF has been implicated in many bacterial infections, however the cell types involved have been difficult to observe in vivo." (PMID 31611882, 2019). "Bacterial infections, associated with endothelial activation due to the innate immune response, increase the expression of pro-inflammatory cytokines like TNF-α and chemokines that also impact on endothelial function." (PMID 30858536, 2019). "These genes mediate the macrophage polarization to M1, a common response of macrophages to bacterial infections, which includes genes encoding TNF, IL-1β, IL-6, and CCL2." (PMID 30064361, 2018). "The product levels of IL-6, TNF-α, and NO in infected cells, which are representative biomaterials associated with bactericidal responses of macrophage to bacterial infection, were used as criteria for identifying differences in responses of infected cells." (PMID 30064361, 2018). "Bacterial infections were shown to trigger caspase-1 associated pyroptosis and TNF-induced necrosis (Blériot and Lecuit, 2016)." (PMID 30280094, 2018). "The expression of IFNγ, IL-27 and TNFα are all increased in sputum from steroid-resistant neutrophilic asthma patients where viral and bacterial infections have been implicated in exacerbations and disease progression." (PMID 27657907, 2016). "IL-2, IL-10, and tumor necrosis factor (TNF) alpha showed weak diagnostic performance in distinguishing between bacterial and non-bacterial infections." (PMID 27486746, 2016). "The pretreatment of blood immune cells with EPs 7630 lowered their secretion of TNF-α and IL-10 and caused an IL-6 dominant response during second stimulation with viral or bacterial infection-mimicking agents." (PMID 26406906, 2015). "Early death during TB treatment is associated with depressed TNFα response to antigenic stimulation and propensity to superadded bacterial infection." (PMID 26567164, 2015). "Patients treated with anti-TNF agents are generally believed to be at increased risk of bacterial infections." (PMID 22405136, 2012). "As anti-TNF agents are more frequently associated with tuberculous infection, this case highlights the need for a high index of suspicion for other severe bacterial infections in patients on immunosuppressants." (PMID 21083879, 2010). "This case highlights the diagnostic complexity of bacterial infections in patients receiving TNF-α inhibitors, where immunosuppression may blunt the expected inflammatory response and delay recognition of systemic infection." (PMID 41531628, 2025).
bacterial infection (continued). "As IL-10 is a cytokine that inhibits inflammation and promotes the production of anti-inflammatory cytokines such as IL-2 and TNF-α, these results suggest that B102 and B116 may help reduce inflammation caused by bacterial infections in the gut." (PMID 41114506, 2025). "In this context, BPI protein may interact with mycobacterial LAM, promoting phagocytosis, inhibiting the production of TNF-α, and causing an anti-inflammatory effect, similar to that observed in GN bacterial infections." (PMID 41008681, 2025). "In human medicine, it has been demonstrated that bacterial infections cause a significant increase in pro-inflammatory cytokines such as TNF-α and IL-1β, which subsequently induce the overexpression of the CALC-1 gene in various tissues, leading to PCT overproduction." (PMID 41012820, 2025). "Both TNF-α and IL-6 increase in bacterial infections, highlighting their diagnostic value in COM38." (PMID 40595978, 2025). "Previous studies have shown that cirrhotic patients with bacterial infection exhibit excessive production of the inflammatory cytokines TNF-α and IL-6, which is associated with the development of an episode of extrahepatic organ failure and in-hospital mortality." (PMID 38413535, 2024). "Additionally, USP18 dampens antibacterial TNF-α signaling and ROS production, increasing the susceptibility to bacterial infections." (PMID 38673764, 2024). "Polyfunctional cytokine profiles (e.g., IFN-γ, TNF, IL-2) are frequently associated with improved outcomes in TB and other bacterial disease models, though to date, a profile that definitively correlates with protection against Mtb is lacking (for review see Lewinsohn, 201767)." (PMID 37898618, 2023). "It is supposed to happen because bacterial infection triggers the release of cytokines that have been associated with the mechanism of labor, including interleukins (IL) IL-1, IL-6, tumor necrosis factor (TNF-a), and prostaglandins (PDE2)." (PMID 37915876, 2023). "IL-17/TNF-α is associated with bacterial infection and neutrophilic infiltration." (PMID 36219481, 2022). "Further study is warranted to elucidate the molecular mechanisms underlying TNF-α-mediated cytotoxic T lymphocyte responses, including cell survival, proliferation, cytokine production, and immune cell exhaustion during intracellular bacterial infection." (PMID 35479068, 2022). "Furthermore, in the fourth phase of ulceration, where there is a bacterial infection and loss of membrane continuity, TNF-α and interleukin one and six cause direct epithelial tissue damage." (PMID 34640462, 2021). "However, it is unclear if the TNFα expression is the result of or a contributor to the bacterial infection and bone loss." (PMID 34831397, 2021). "This phenomenon is probably because, usually, the level of procalcitonin increases in the presence of cytokines, caused by a bacterial infection (IL-1b, TNF-a, and IL-6), and its production is regulated by the signal transducer and activator of transcription 3 (STAT-3)." (PMID 34439009, 2021). "Also, treatment with øKp_Pokalde_002 resulted in a significant reduction of pro-inflammatory cytokines (TNF-α and IL-6) caused by bacterial infection, thereby reducing the tissue inflammation." (PMID 34485172, 2021). "Additionally, OnGal8-L overexpression reduced the expression of IL-1β, TNF-α caused by bacterial infection." (PMID 32676073, 2020). "Proinflammatory cytokines (such as IL-6 and TNF-α) play an important role in the regulation of enteric pathogenic bacteria and the concentration of these cytokines in the serum of animals is usually increased after enteric pathogenic bacterial infection." (PMID 31126046, 2019). "In accordance with the hygiene hypothesis, our findings suggest that, with the exception of TNF-α, maternal viral and bacterial infections during pregnancy may be associated with lower levels of inflammation among adult offspring." (PMID 30923624, 2019).
bacterial infection (continued). "Pathogenic levels of TNF-α might be neutralized efficiently while maintaining the minimal levels needed to control host resistance to bacterial infection." (PMID 29184553, 2017). "TNF-α has been linked to the defense against some bacterial infections." (PMID 25410206, 2015). "Excessive activation of microglia due to pathogenic bacterial infection or injury releases proinflammatory mediators such as tumor necrosis factor (TNF)-α, interleukin (IL)-1β, IL-6, reactive oxygen species (ROS), nitric oxide (NO), inducible NO synthase (iNOS) and cyclooxygenase (COX)-2." (PMID 25514974, 2014). "However, loss of TRPV1 function has been associated with increased production of TNFα upon bacterial infection." (PMID 25242870, 2014). "TNF-α and IL-8 are pro-inflammatory cytokines that have numerous biological activities and play important roles not only in host defence but also in some of the pathological sequelae associated with various bacterial infections." (PMID 24107297, 2013). "To study the impact of bacterial infection on host immunological responses, we monitored mRNA levels of genes encoding inflammation markers TNFα, IL-1β, IL-22 and IL-10, including pro- and anti-inflammatory cytokines, in axenic and infected zebrafish larvae at 1, 2 and 3 dpi." (PMID 22911651, 2012). "The combination of increased TNF-α production and maintenance of its cognate receptor on the cell surface likely contributes to the cytokine “surge” and exacerbates the pathology associated with bacterial infection." (PMID 20011115, 2009). "IL-6,stimulated by TNF-α, IL-1, and endotoxin of viral and bacterial infections,acts as a T-cell activation indicator, induces antibody secretion by humanB-cells, causes differentiation of cytotoxic T-cells, and also has the abilityto inhibit TNF-α production." (PMID 18274637, 2007). "Moreover, CTRP9 knockdown reduced the frequency of Granzyme B-producing T cells, impaired the transcriptional upregulation of Perforin A, Granzyme B, TNF-α, and IL-6, ultimately resulting in increased susceptibility to bacterial infection and elevated mortality." (PMID 41249580, 2025). "Besides, anti-TNF-α therapy rendered patients susceptible to bacterial infection." (PMID 36249423, 2022). "Abnormal mechanical stress, sudden trauma, bacterial infection, smoking, aging, and other pathogenic factors lead to the increased expression of inflammatory cytokines (such as interleukin (IL)-1β, IL-6, IL-17, and tumor necrosis factor-α (TNF-α)) in nucleus pulposus (NP) cells." (PMID 36388163, 2022). "Collectively, our results suggest that the short-term benefit of ADAM17 inhibition might lead to enhanced secretion of IFNγ, while long-term inhibition of ADAM17 might be detrimental and could increase the risk of bacterial infection due to drastic decrease in soluble TNFα." (PMID 26683521, 2015). "Moreover, our study provided compelling evidence that TLR signaling plays an essential and fundamental role in hemocyte activation and TNF induction caused by bacterial infection, revealing that TLR-mediated innate immunity shared an ancient origin at least in bilateria phylum." (PMID 24098508, 2013). "For example, bacterial infections induce inflammation through recognition by dedicated PRRs as well as through virulence factors resulting in high levels of TNF‐α, IL‐6 and acute phase response proteins." (PMID 36800487, 2025). "We found that the expression levels and secretion levels of IL-6, TNF-α and IL-1β were greater in Gpnmb-deficient THP-1 cells than in sgCtrl THP-1 cells upon bacterial infection." (PMID 40038549, 2025). "Anaerobic bacterial infections induce local and systemic increases of proinflammatory cytokines including TNF-α, IL-1β, and IL-6." (PMID 40552326, 2025). "Bacterial infection induces endotoxin production, which stimulates macrophages to produce high levels of pro-inflammatory cytokines, including TNF-α, IL-6, and IL-1β." (PMID 39625293, 2025).